SAA1 (serum amyloid A1)
Diseases named in the same sentence as SAA1 in open-access papers (continued):
Sharing a sentence is not in itself a finding about the gene and the disease.
ovarian carcinoma (9 papers, 2010 to 2026). A malignant neoplasm originating from the surface ovarian epithelium. "KEY POINTS: A distinct SAA1-enriched tumour cell subset with metastasis-associated features is identified in ovarian cancer." (PMID 42145073, 2026). "SAA1 in ovarian cancer cells has been linked to the recruitment and differentiation of MDSCs, prompting further investigation into the underlying mechanisms." (PMID 41029721, 2025). "In vivo validation using a C57BL/6 mouse peritoneal tumor model confirmed that SAA1 promotes the development of a tumor-promoting immunosuppressive microenvironment that facilitates the formation of ovarian cancer-associated ascites." (PMID 41029721, 2025). "Accumulation of serum amyloid A (SAA1/2) is associated with inflammation in epithelial ovarian cancer, via the TNF-alpha mediated activation of NF-κB." (PMID 30274280, 2018). "Nonetheless, no study has elucidated the specific role and underlying mechanisms of SAA1 in ovarian cancer or whether SAA1 can regulate MDSCs to facilitate the development of a tumor-promoting immunosuppressive microenvironment." (PMID 41029721, 2025). "Additionally, in ovarian cancer, SAA1 has been implicated as a potential biomarker for metastasis, further highlighting its significance in cancer biology." (PMID 40565234, 2025). "SAA1 directly enhances key malignant behaviors of ovarian cancer cells, including proliferation, migration, and invasion." (PMID 41029721, 2025). "This secreted IL-1β further amplifies SAA1 expression in ovarian cancer cells through IL-1R/NF-κB signaling, thereby forming a positive feedback loop that reinforces a tumor-promoting immunosuppressive microenvironment conducive to immune evasion." (PMID 41029721, 2025). "To further elucidate the pivotal role of SAA1 in ovarian carcinogenesis in vivo, we employed CRISPR/Cas9 technology to generate a murine ovarian cancer ID8 cell line with SAA1 knockout (SAA1-KO)." (PMID 41029721, 2025). "Utilizing the TCGA database, we scored the immune microenvironment of ovarian cancer based on the expression levels of SAA1." (PMID 41029721, 2025). "This mechanistic insight reveals how the SAA1-IL-1β feedback loop between ovarian cancer cells and MDSCs contributes to immune evasion." (PMID 41029721, 2025). "In turn, IL-1β binds to IL-1R on ovarian cancer cells, activating the NF-κB pathway and further stimulating SAA1 production." (PMID 41029721, 2025). "To further investigate the role of SAA1 in ovarian cancer progression, we transfected a luciferase plasmid into SAA1-knockdown murine ovarian cancer cell line ID8 for in vivo imaging." (PMID 41029721, 2025). "These bioinformatics analysis results provide initial insights into the significant correlation between SAA1 and MDSCs, underscoring its pivotal role in the immune microenvironment of ovarian cancer." (PMID 41029721, 2025). "The results confirmed that IL-1β significantly upregulated both the expression and secretion of SAA1 in ovarian cancer cells." (PMID 41029721, 2025). "Consistently, analysis of public databases revealed a significant association between high SAA1 expression and both advanced FIGO stage and higher histological grade in ovarian cancer patients." (PMID 41029721, 2025). "SAA1 was significantly upregulated in ovarian cancer cells after interaction with MDSCs and confirmed in tumor samples and cell lines." (PMID 41029721, 2025). "Subsequent experiments validated that SAA1, at both the RNA and protein levels, exhibited substantial upregulation in ovarian cancer cells and tissues." (PMID 41029721, 2025). "In turn, IL-1β acts on ovarian cancer cells to enhance SAA1 expression and release via the IL-1β/IL-1R/NF-κB signaling pathway." (PMID 41029721, 2025). "To delve deeper into the biological role of SAA1 in ovarian cancer cells, we designed three short hairpin RNAs (shRNAs) targeting SAA1 and established a stable SAA1-knockdown A2780 cell line via lentiviral transfection." (PMID 41029721, 2025).
ovarian carcinoma (continued). "Subsequent analyses using CCK-8 assays and EdU assays revealed that SAA1 knockdown significantly inhibited the proliferation of ovarian cancer cells, while overexpression of SAA1 markedly promoted their proliferation." (PMID 41029721, 2025). "It was observed that SAA1 was markedly upregulated in ovarian cancer cells when co-cultured with MDSCs." (PMID 41029721, 2025). "Conversely, overexpression of SAA1 in ovarian cancer cells SKOV3 led to a substantial enhancement in the recruitment of MDSCs by their supernatants." (PMID 41029721, 2025). "Lastly, the therapeutic efficacy of targeting SAA1 and IL-1β in ovarian cancer immunotherapy warrants further comprehensive investigation." (PMID 41029721, 2025). "In conclusion, ovarian cancer cells release SAA1, which acts on the TLR2/4 on the surface of MDSCs, thereby recruiting MDSCs and promoting the differentiation of GMPs into MDSCs." (PMID 41029721, 2025). "In conclusion, this study elucidates the multifaceted tumor-promoting role of SAA1 in the pathogenesis of ovarian cancer." (PMID 41029721, 2025). "In this study, we initially observed a significant accumulation of MDSCs in patients with ovarian cancer, along with a notable upregulation of SAA1." (PMID 41029721, 2025). "Additional functional experiments demonstrated that SAA1 significantly enhanced the proliferation, migration, and invasion of ovarian cancer cells." (PMID 41029721, 2025). "Collectively, these experiments affirm that SAA1, despite being a secreted protein, plays a crucial role in sustaining the malignant phenotype of ovarian cancer cells." (PMID 41029721, 2025). "Meanwhile, as SAA1 was knocked down or overexpressed in ovarian cancer cells, the ELISA results further confirmed that SAA1 in the cell supernatants was also decreased or increased with it." (PMID 41029721, 2025). "Our study reveals that SAA1 regulates IL-1β secretion by MDSCs through TLR2/4, while the secreted IL-1β in turn stimulates SAA1 production in ovarian cancer cells, thereby establishing a positive feedback loop between these components." (PMID 41029721, 2025). "Results revealed that the knockdown of SAA1 in ovarian cancer cells significantly diminished the ability of cell supernatants to recruit MDSCs." (PMID 41029721, 2025). "In short, our findings indicate that SAA1 promotes the metastasis of ovarian cancer cells through the EMT pathway in vitro." (PMID 41029721, 2025). "Bioinformatics analyses indicate a robust correlation between SAA1 and the immunosuppressive microenvironment in ovarian cancer patients, with a primary focus on MDSCs." (PMID 41029721, 2025). "In conclusion, these findings establish the crucial role of SAA1 in the recruitment and differentiation of MDSCs in ovarian cancer." (PMID 41029721, 2025). "This recruitment ability was notably reduced after knocking down SAA1 in ovarian cancer cells A2780 and ID8." (PMID 41029721, 2025). "The results confirmed that SAA1 released from ovarian cancer cells indeed promotes the recruitment and activation of MDSCs through its interaction with TLR2/4 on the surface of MDSCs." (PMID 41029721, 2025). "In summary, these results strongly suggest that SAA1 promotes the proliferation and clonogenic capacity of ovarian cancer cells in vitro." (PMID 41029721, 2025). "The application of the NF-κB pathway inhibitor APDC markedly suppressed IL-1β-induced SAA1 secretion in ovarian cancer cells." (PMID 41029721, 2025). "These experiments confirm that SAA1 released by ovarian cancer cells acts on TLR2/4 on the surface of MDSCs, thereby promoting MDSCs recruitment and the differentiation of GMPs into MDSCs." (PMID 41029721, 2025). "This study uncovers a novel SAA1–IL-1β feedback loop that promotes immunosuppression and progression in ovarian cancer." (PMID 41029721, 2025). "Co-culture experiments further demonstrated that ovarian cancer cells recruit and activate MDSCs via SAA1 secretion, which engages TLR2/4 on MDSCs and induces IL-1β production." (PMID 41029721, 2025).
ovarian carcinoma (continued). "Other factors linking inflammation and epithelial ovarian cancer, include serum amyloid A (SAA1/2) and macrophage migration inhibitory factors (MIF)." (PMID 30274280, 2018). "The SAA1-TAM-CXCL1 axis facilitates metastatic progression in ovarian cancer." (PMID 42145073, 2026). "Considering that IL-1β is also a potent inducer of SAA1 release, we further investigated whether IL-1β secreted by MDSCs could, in turn, stimulate SAA1 production in ovarian cancer cells." (PMID 41029721, 2025). "While this study, for the first time, uncovers that ovarian cancer cells and MDSCs form a positive feedback loop through the SAA1-IL-1β axis to promote immune evasion, thereby providing a new target for ovarian cancer diagnosis and treatment, there are still some limitations." (PMID 41029721, 2025). "Furthermore, SAA1 was markedly upregulated in ovarian cancer cell lines (SKOV3, HEY, ES-2, A2780) compared to the normal ovarian epithelial cell line IOSE, at both mRNA and protein levels." (PMID 41029721, 2025). "IL-1β, in turn, upregulates SAA1 expression in ovarian cancer cells, establishing a positive feedback loop that promotes the formation of a tumor-promoting immunosuppressive microenvironment and drives ovarian cancer progression." (PMID 41029721, 2025). "To investigate whether SAA1 released by ovarian cancer cells could recruit MDSCs, we collected cell supernatants from ovarian cancer cells and placed them in the lower chamber of a co-culture system, and MDSCs in the upper chamber." (PMID 41029721, 2025). "Furthermore, we conducted Transwell assays to investigate the potential role of SAA1 in the metastatic process of ovarian cancer cells." (PMID 41029721, 2025). "Firstly, despite SAA1 being a secreted protein, it remains unclear whether it can regulate the secretion of other cytokines by ovarian cancer cells, thereby influencing MDSCs." (PMID 41029721, 2025). "A recent study proposes SAA1 as a potential marker for ovarian cancer metastasis." (PMID 41029721, 2025). "Thus, ovarian cancer cells were co-cultured with MDSCs to investigate the impact of SAA1 on MDSCs recruitment and activation." (PMID 41029721, 2025). "However, a more in-depth exploration of the role that SAA1 plays in the immune microenvironment of ovarian cancer is warranted." (PMID 41029721, 2025). "Some identified peaks corresponded to some newly discovered ovarian cancer biomarkers, such as peaks 11,684.09 and 11,528.53 that have been identified as serum amyloid A1 and were found to be up regulated in cancer patients in comparison to patients with benign masses." (PMID 31870100, 2019). "Moreover, clonogenic assays were employed to assess the impact of SAA1 on the clonogenic capacity of ovarian cancer cells, demonstrating that SAA1 knockdown led to a substantial decrease in clonogenicity, whereas SAA1 overexpression significantly enhanced this capacity." (PMID 41029721, 2025). "Therefore, we hypothesized that SAA1 released by ovarian cancer cells could recruit MDSCs and facilitate the differentiation of GMPs into MDSCs via TLR2/4 on MDSCs." (PMID 41029721, 2025). "Furthermore, a stable murine ovarian cancer cell line (ID8) with SAA1 knockdown was established." (PMID 41029721, 2025). "In addition, the SAA1 promotes ovarian cancer cell migration by regulating MMPs and EMT which may correlate with AKT pathway activation." (PMID 37081987, 2023). "Consistent with our findings in human ovarian cancer cells, CCK-8 assays, EdU assays, and clonogenic assays in ID8 cells corroborated that SAA1 knockdown significantly inhibited proliferation and clonogenic capacity." (PMID 41029721, 2025). "In our study, SAA1 was found to significantly affect the EMT pathway in ovarian cancer cells, which is consistent with a previous study revealing that arecoline induced EMT and promoted oral cancer metastasis through SAA1 expression." (PMID 41029721, 2025).
ovarian carcinoma (continued). "Further exploration in the Kaplan Meier database indicated that elevated SAA1 expression also correlated with shorter Recurrence-Free Survival (RFS) and Post-Progression Survival (PPS) in ovarian cancer patients." (PMID 41029721, 2025). "Collectively, this study identifies a novel SAA1-TAM-CXCL1 immune-inflammatory signalling axis, elucidates its critical role in ovarian cancer metastasis, and provides a robust theoretical foundation for the development of innovative anti-metastatic therapeutic strategies." (PMID 42145073, 2026). "Taken together, our research suggests that ovarian cancer cells secrete SAA1, which interacts with TLR2/4 on the surface of MDSCs, not only promoting MDSCs recruitment and GMP differentiation into MDSCs but also enhancing IL-1β secretion by MDSCs." (PMID 41029721, 2025). "In addition, analysis revealed a positive correlation between SAA1 and IL1B expression in ovarian cancer tissues." (PMID 41029721, 2025). "Normal human ovarian tissues express little or no SAA1/2, whereas, ovarian cancers express high levels of SAA1/2." (PMID 30274280, 2018).
depression (8 papers, 2019 to 2025). "Recent research highlights elevated SAA1 levels in the plasma of patients with clinical depression compared to controls, indicating a potential link between SAA levels and depressive states." (PMID 38377025, 2024). "In rodents, liver-specific SAA1 overexpressing mice were considered a valuable model to study depression." (PMID 36188478, 2022). "SAA1 can cross the BBB, promote the aggregation of brain Aβ protein, and induce an increase in the number of microglia in the brain and pro‐inflammatory factor expression levels, leading to depression‐like behavioral changes in mice." (PMID 40537921, 2025). "For example, proteomic research suggests that the serum levels of c-reaction protein (CRP), inter-alpha-trypsin inhibitor heavy chain H4 (ITIH4), serum amyloid A1 (SAA1), and angiopoietin-like 3 (ANGPTL3) are significantly higher in patients with depression than in healthy controls." (PMID 31719821, 2019).
glioblastoma (8 papers, 2018 to 2024). The most malignant astrocytic tumor (WHO grade IV). "In summary, our results demonstrate that SAA1 in combination with integrin αV and β3 can serve as an indicator of high glioblastoma risk." (PMID 29603594, 2018). "The study revealed that SAA1 was upregulated 10 to 60 times in patients with glioblastomas compared with patients with non‐neoplastic and other grades of astrocytoma." (PMID 29603594, 2018). "Focusing the attention on the five non-blood proteins, it is worthy of mention that they include four histones, highly basic proteins correlated with the onset of several tumors, and the serum amyloid A1 protein, an acute-phase inflammation protein upregulated in human glioblastoma." (PMID 35216175, 2022). "Besides, the combination of serum amyloid A1 and integrin αvβ3 increased cell migration and progression in glioblastoma cells." (PMID 35038961, 2022). "The correlation of SAA1 with human glioblastomas was proposed in a recent study." (PMID 29603594, 2018). "According to the study, SAA1 and TIMP1 can be considered as biomarkers or therapeutic targets for monitoring patient treatment response for glioblastoma." (PMID 30867991, 2019). "We selected 15 hub genes with higher degrees of connectivity, including tissue inhibitors metalloproteinases-1 and serum amyloid A1; additionally, we used GSE53733 containing 70 glioblastoma samples to conduct Gene Set Enrichment Analysis." (PMID 30867991, 2019).
systemic amyloidosis (8 papers, 2006 to 2023). "High levels of SAA1 are thought to be the cause of organ damage in diseases such as systemic amyloidosis and Alzheimer's disease." (PMID 33854635, 2021). "Naturally occurring systemic amyloidosis due to misfolded SAA1 has been reported in humans (Homo sapiens) and the common bottlenose dolphin (Tursiops truncatus)." (PMID 37800590, 2023). "Our studies on protein misfolding propensity of the signal peptide region allow us to better understand the mechanism behind systemic amyloidosis in the SAA1 protein." (PMID 35664543, 2022). "To better understand the mechanism behind systemic amyloidosis in the SAA1 protein, we studied the misfolding propensity of the signal peptide region." (PMID 35664543, 2022). "We then studied different signal peptide regions of SAA1 amino acid sequences from various animal species to validate the propensity to misfold in animals with a high and low occurrence of systemic amyloidosis." (PMID 35664543, 2022). "Synthetic SAA1 signal peptides were designed from amino acid sequences of diverse animal species to correlate the experimental amyloidogenicity with the occurrence of systemic amyloidosis described in case reports." (PMID 35664543, 2022). "All SAA1 signal synthetic peptides designed from the different animal species had the propensity to misfold and form fibrils, particularly in species with low occurrence of systemic amyloidosis." (PMID 35664543, 2022). "Several of the SAA1 signal peptides studied come from the amino acid sequence of reptiles and fish where no cases of systemic amyloidosis have been recorded: for example, Sterlet Fish (Acipenser ruthenus) (signal peptide 5) and Chinese Softshell Turtle (Pelodiscus sinensis) (signal peptide 12)." (PMID 35664543, 2022).
asthma (7 papers, 2016 to 2025). "Both CRP and hs-CRP have shown diagnostic value for asthma, while SAA1 has also been linked to lung diseases." (PMID 40915180, 2025). "In the EGPA vs. asthma analysis, SAA1, FGA, SAP, and CEPT alone had slightly lower sensitivity but still showed good AUC and specificity." (PMID 35757752, 2022). "KEGG functional analysis revealed that MMP1 was enriched in autoimmune thyroid disease and cell adhesion molecule cams, SAA1 was enriched in autoimmune thyroid disease and cell adhesion molecule cams, and PLAU was enriched in asthma and the citrate cycle." (PMID 39744064, 2024). "SAA1, FGA, SAP, and CETP can be potentially useful biomarkers for early diagnosis of EGPA and differential diagnosis of asthma." (PMID 37215720, 2023). "We have identified and validated four new potential serum biomarkers, including SAA1, FGA, SAP, and CETP, that can be used to distinguish EGPA from severe asthma." (PMID 35757752, 2022). "The combination of SAA1, FGA, SAP, and CETP as biomarkers for differential diagnosis of asthma had an AUC of 0.921, a sensitivity of 78.13%, and a specificity of 100%, which were all larger than single markers." (PMID 35757752, 2022). "The serum levels of SAA1, FGA, and SAP in the EGPA group were significantly elevated as compared to the healthy control and severe-asthma groups, while the serum CETP was significantly lower in the EGPA group compared with the severe-asthma group." (PMID 35757752, 2022). "Both DIA and PRM approaches applied in our study showed that serum SAA1 level in the EGPA group was not only significantly higher than that in the healthy control group, which was consistent with the previous study, but also significantly higher than the severe-asthma group." (PMID 35757752, 2022).